ENSG00000252352
Gene: Small nucleolar RNA gene on chromosome 17 (69,355,133 to 69,355,218, reverse strand). Ensembl gene ENSG00000252352.
Gene Ontology:
Biological process: RNA processing
Cellular component: nucleolus
Homologues: Paralogues in human: SNORA40B (86% identical), SNORA40 (84% identical), SNORA40C (80% identical).